FOXA1 (forkhead box A1)
Diseases named in the same sentence as FOXA1 in open-access papers (continued):
Sharing a sentence is not in itself a finding about the gene and the disease.
tumor (continued). "In summary, our findings support a regulatory role for FOXA1 in tumor proliferation via the regulation of IGFBP-3 expression in PC." (PMID 22879989, 2012). "Quantitative RT-PCR analysis of SCaBER cells established from a primary SCC tumor showed that FOXA1 expression was significantly lower in these when compared to RT4." (PMID 22590586, 2012). "Bioinformatic analysis of mRNA targets of the altered miRNAs, identified oncogenes like ERBB2, YY1, several MAP kinases, and known tumor-suppressors like FOXA1 and SMAD4." (PMID 22438871, 2012). "In this study, we provide the first evidence linking alterations in FOXA1 expression to advanced tumor stage and high histologic grade." (PMID 22590586, 2012). "Upregulation of FOXA1 also was confirmed by Q-RT-PCR in a larger tumor sample set (n = 8) as well as at the protein level by immunohistochemical staining." (PMID 20565980, 2010). "In the whole series, we verified that patients harbouring FOXA1-positive tumours show a better disease-free survival." (PMID 19549328, 2009). "Among FOXA1-positive tumours, 83.1% are comprised in the luminal A subtype, similar to GATA-3 where 87.7% of positive tumours were classified within this molecular subtype." (PMID 19549328, 2009). "We found that mRNA levels deceased significantly in the LADY tumor but that staining for FoxA1 protein was undiminished." (PMID 17343742, 2007). "Quantitative RT-PCR showed diminished FoxA1 mRNA expression that contrasted with increased staining for FoxA1 protein in the LADY tumor." (PMID 17343742, 2007). "For instance, BMI1-driven PI3K/Akt activation could attenuate FOXA1’s tumor-suppressive effects, thereby influencing tumor aggressiveness and therapeutic outcomes." (PMID 40623983, 2025). "In conclusion, our study reveals the luminal-associated transcriptional program (FOXA1-EHF-ITGB4) with FOXA1 as the core regulator, as well as its downstream pathway (ECM-receptor interaction), which affects immune communication, mucus production, and tumor risk in IMA." (PMID 39584073, 2025). "We subsequently analyzed the effects of each class of FOXA1 alteration on tumor transcriptomes." (PMID 39745364, 2025). "Whether and how this specific impairment of FOXA1 transcriptional function may impact tumor prognosis and treatment is still unknown but it deserves close attention for its potential clinical relevance." (PMID 39633177, 2025). "However, this study does not involve changes in the Forkhead domain and mainly investigates the impact of basal FOXA1 levels on tumor biology, given that PC-3 and DU145 are AR-negative cell lines." (PMID 41330917, 2025). "In the xenograft model, the co-knockdown of FOXA1 and BMI1 in CNE1 cells resulted in an increased sensitivity to cisplatin, as indicated by reduced tumor size and decelerated growth rates, in stark comparison to the FOXA1-knockdown cells that displayed resistance." (PMID 40623983, 2025). "The exact way that FOXA1 influences tumor chemoresistance and prognosis is still under debate." (PMID 41283251, 2025). "The coordinated control of FOXA1 stability by these factors links oxygen sensing to androgen signaling and highlights a regulatory axis that may contribute to tumor progression and metastatic potential." (PMID 40643528, 2025). "Notably, overexpression of the miRNA signature downregulated the Androgen Receptor (AR) expression via WT1 and FOXA1 repression, impaired the tumor-sphere forming ability of cells and was able to reverse cancer stemness." (PMID 40399259, 2025). "Based on molecular profiling and TME analysis via quanTIseq, our findings indicate that FOXA1 alterations may regulate tumor cell–extrinsic properties." (PMID 39745364, 2025). "The transcription factor FOXA1 has been extensively studied for its role in tumorigenesis and cancer progression, exhibiting context-dependent functions that can range from promoting to suppressing tumor growth." (PMID 40623983, 2025).
tumor (continued). "Moreover, the xenograft tumor model showed that the increased tumor growth rate, consequent to FOXA1 knockdown, was significantly reversed by the knockdown of BMI1." (PMID 40623983, 2025). "The tumor cells tested positive for the androgen receptor, FOXA1, and GCDFP15." (PMID 40722519, 2025). "The systematic identification and comprehensive characterization of FOXA1 transcriptional targets in NPC is essential to delineate its functional contributions to tumor progression and therapeutic resistance, while uncovering the molecular mechanisms that orchestrate these pathological processes." (PMID 40623983, 2025). "Under high SLC7A11 expression, moderate inhibition of FOXA1 may enhance tumor cell survival, while at basal levels, it appears to have a suppressive effect." (PMID 41330917, 2025). "The tumor-promoting effects of FOXA1 were validated through MTS assay and colony formation assay." (PMID 41395253, 2025). "As a transcription factor, FOXA1 can maintain a “luminal” tumor phenotype." (PMID 41283251, 2025). "Moreover, we observed mutations in genes frequently associated with PC, such as SPOP, FOXA1, and KMT2C, in the tumor organoids." (PMID 40163511, 2025). "In addition, 60% of TNBC samples were classified as basal-like (based on CK5/6 and/or EGFR expression in >10% of tumor cells) and 36% had a molecular apocrine phenotype (based on positive staining for AR and FOXA1 in ≥1% of tumor cells)." (PMID 39723208, 2024). "This dynamic may help reconcile seemingly divergent roles of FOXA1 as both an oncogene and a tumor suppressor." (PMID 38528115, 2024). "Furthermore, the clonal FOXA1 mutation was observed with a VAF of 26.6%, confirming the presence of a high proportion of circulating tumor DNA." (PMID 38355834, 2024). "Absence of GATA3/FOXA1 co-expression (GATA3-/FOXA1-) was associated with tumor extensive necrosis (P=0.001) after Bonferroni correction for multiple comparisons." (PMID 38425344, 2024). "Previous studies have indicated a high expression of FOXA1 in various tumor tissues and its pivotal role in biological processes such as the cell cycle, epithelial differentiation, and metabolism, suggesting its potential association with genomic instability in cancer cells." (PMID 39440050, 2024). "However, sexually dimorphic HCC was completely reversed in FOXA1- and FOXA2-deficient mice, with tumor volume becoming larger in FOXA1- and FOXA2-deficient female mice, and conversely, tumor volume was decreased in male mice." (PMID 38605023, 2024). "In contrast to the parental tumors which exhibited high sensitivity to TKI treatments, the FOXA1-knockout tumors displayed 10%–30% tumor growth and maintained higher expression of squamous markers upon drug treatments, indicating that FOXA1 knockout at least partially conferred TKI resistance." (PMID 39687207, 2024). "In conclusion, our study revealed that the absence of GATA3/FOXA1 expression is linked to tumor extensive necrosis and poor prognosis in UTUC." (PMID 38425344, 2024). "Recent findings indicate a strong correlation between FOXA1 and tumor resistance." (PMID 39440051, 2024). "FOXA1 is mainly highly expressed in tumor sites; compared to other immune cells, T follicular helper T-FH cells and Mast Cells have significantly higher levels of infiltration around tumors with high FOXA1 expression." (PMID 39440050, 2024). "Moreover, they claimed that the tumor-suppressive function of EAF2 is partly mediated through interaction with FOXA1." (PMID 39588149, 2024). "In addition, the high expression of mRNA in the FOXA1, FOXM1, and FOXP1 was significantly associated with tumor stage in BRCA tissues." (PMID 38608123, 2024). "Involvement of FOX family in PCa formation and metastasis has been reported in numerous cases, of which FOXA1 is essential in regulating AR-mediated tumor development, and other FOX members have been confirmed to play regulatory roles in progression of various cancers." (PMID 38057852, 2023).
tumor (continued). "KTB42- HRasG12V + SV40-T/t cell-derived tumor was ERα−/GATA3−/FOXA1−, and CK8−/CK14−/CK19−." (PMID 37709737, 2023). "Therefore, the comparisons of AGR2 and FOXA1 levels between tumor tissues and adjacent tissues were performed among 549 and 541 patients, respectively." (PMID 37568077, 2023). "A similar pattern of IHC staining for PCNA and FOXA1 protein levels was observed upon SKP2 inhibition, suggesting that SKP2 regulation of FOXA1 may, in turn, drive tumor proliferation and serve as in vivo validation for our in vitro findings." (PMID 37491794, 2023). "In short, these data imply that KRT7-AS reduces expression of oncogenic KRT7 and downstream tumorigenic FOXA1 in cancer tissues and cells, implying that inhibition of oncogenic KRT7 and FOXA1 is one of the mechanisms underlying KRT7-AS-mediated tumor suppression and pro-apoptosis." (PMID 37185462, 2023). "Since FOXA1 reduced the efficacy of anti-angiogenesis therapy against experimental lung xenograft tumor, we assumed that it expression level might be related to the efficacy of anti-angiogenesis therapy in LUAD patients." (PMID 35974000, 2022). "In addition to its putative role in lineage plasticity, we identified FOXA1 as a tumor cell-intrinsic repressor of ISG expression, exemplified by PD-L1." (PMID 36323682, 2022). "However, co-transduction of FOXA1 and HOXB13 together ultimately results in the most dramatic shift in the AR cistrome away from normal prostate-associated AR binding sites towards tumor-associated AR binding sites." (PMID 36212399, 2022). "Many studies have focused on the role of FOXA1 in human cancers, where its function is tissue specific and it may behave as a tumor suppressor or oncogene." (PMID 35163157, 2022). "We further demonstrated that the tumor suppressive effect of lncRNA RGMB-AS1 can be mediated through direct binding with FOXA1, which added a new perspective to the role of inhibition of NPC occurrence, and thus provided a potential target for the diagnosis, treatment and prognosis of NPC." (PMID 35184697, 2022). "Moreover, FOXA1 was positively correlated with MHC genes, immunosuppressive genes, immune activating genes, and chemokine receptors, indicating a pivotal role of FOXA1 in tumor immunomodulatory function, especially in TCGA-OV cohort." (PMID 36393971, 2022). "Taken together, FOXA1 might influence the viability, proliferation, and invasion of tumor cells by affecting different signaling pathways in different cancers, leading to various effects on EMT." (PMID 36393971, 2022). "Moreover, the upregulation of FOXA1 inhibits GC cells proliferation and tumor formation, and also promotes apoptosis." (PMID 35163157, 2022). "The function of FOXA1 in tumor development and progression is a matter of ongoing debate." (PMID 36230619, 2022). "Silencing FOXA1 or FOXD1 in RCC inhibits tumor growth by inhibiting cell cycle progression." (PMID 36585925, 2022). "Furthermore, LAR tumours and cell line models display high dependencies on AR, FOXA1, ERBB2, and AKT protein and phospho-protein signalling, as well as frequent PIK3CA and ERBB2 mutations." (PMID 36077812, 2022). "Therefore, we employed a xenograft tumor model to study the response of FOXA1-expressing tumors to anti-angiogenesis agents." (PMID 35974000, 2022). "Furthermore, mir-17 and 20a positively correlate with MYC and MIR17HG, and, conversely, negatively correlated with FOXA1 in overall primary tumor samples." (PMID 36550153, 2022). ".The findings proved that FOXA1+ Tregs could inhibit the antitumor immunity of T cells and promote tumor growth by the IFN‐β‐PI3K‐Akt‐FOXA1 signaling pathway." (PMID 35474948, 2022). "FOXA1+ Tregs could inhibit the antitumor immunity of T cells and promote tumor growth by the IFN‐β‐PI3K‐Akt‐FOXA1 signaling pathway." (PMID 35474948, 2022).
tumor (continued). "Using unsupervised hierarchical clustering of six subtyping genes assessed by multiplex RNA hybridization (basal differentiation: KRT5, KRT14, CD44; luminal differentiation: KRT20, GATA3, and FOXA1), 28 tumor samples were each classified as either basal or luminal subtypes." (PMID 36142180, 2022). "Because FOXA1 enhanced LUAD cells survival in nutrients deprived conditions in vitro, we hypothesized that FOXA1 might influence the xenograft tumor survival in vivo when the nutrients supply in tumors was cut off by anti-angiogenic therapy." (PMID 35974000, 2022). "Moreover, one of the possible explanations suggested regarding the acquired resistance to HER2-targeted therapies in BC patients was a link between JAM-A, β-catenin, and FOXA1 that triggers HER2-independent tumor proliferation via HER3 activation." (PMID 36230619, 2022). "Finally, despite the extensive squamous morphology evident in this tumor, some cells within clusters 1–3 had relatively high expression of FOXA1, suggesting that a subset of tumor cells continued to express luminal differentiation markers." (PMID 36323682, 2022). "Additionally, in cooperation with other TFs, FOXA1 facilitates the oncogenic switch of AR signalling, yet its expression has a tumour-suppressive impact on the progression of primary PCa to NEPC." (PMID 34940756, 2021). "IHC data indicated that 60.6% of the tumors had a basal-like phenotype (i.e., a TNBC tumor that expresses at least one of the two basal markers, EGFR and CK5/6) and 36.5% of the tumors had a molecular apocrine phenotype (i.e., a TNBC tumor that expresses both AR and FOXA1)." (PMID 33673133, 2021). "Thus, discerning the mechanisms that regulate FOXA1 expression and precisely identifying the tumor types that would respond favorably to FOXA1 inhibition will be essential and require more sophisticated model systems reflecting the complex hormonal milieu." (PMID 34680352, 2021). "FOXA1 is considered one of key modulators of this reprogramming in ER-positive therapy-resistant tumors as it modulates the expression levels of ER-regulated genes, some of which, in turn, can make a tumor more aggressive." (PMID 33417085, 2021). "Moreover, tumors with molecular apocrine phenotype, i.e., expressing both AR and FOXA1 biomarkers, exhibited significantly lower density of intra-tumor CD11b- or CXCR2-positive cells (p = 0.001 and p = 0.006, respectively)." (PMID 34066060, 2021). "The finding that FOXA1 activates KDM6A transcription prompted us to investigate whether the KDM6A-ARHGDIB axis mediates the tumour-suppressive effect of FOXA1 in BCa cells." (PMID 34006303, 2021). "Two types of translocation events involving the FOXA1 CREs emerge in these tumours." (PMID 32946061, 2021). "Conversely, FOXA1 suppresses more primitive tumor cell phenotypes, such as migration and invasion." (PMID 34680352, 2021). "As a result, increased FOXA1 suppresses the tumor immune response." (PMID 34680352, 2021). "We then asked whether upregulation of RASGRP3 or FOXN3 contribute to the tumor suppressive role of FOXA1 in NPC cells." (PMID 32201519, 2020). "Taking these results together, FoxA1 may exert tumor suppressive roles in CCA via the inhibition of cell proliferation and invasion activities." (PMID 32151057, 2020). "Indeed, the tumor tissue of UPN1 showed higher FOXA1 expression at both the mRNA level and the protein level." (PMID 32235312, 2020). "Mutations with high VAFs indicated early appearance during tumorigenesis or tremendous contribution to later expansion of tumor cells, and the previous study demonstrated AKT1, CBFB, MAP2K4, ARID1A, FOXA1, and PIK3CA mutations have relatively high average VAFs in breast cancers." (PMID 33173047, 2020). "FOXA1 could act as a tumor suppressor in human cancers, and its expression is associated with the prognosis of patients with cancers." (PMID 32293494, 2020).
tumor (continued). "As a tumor suppressor, FOXA1 overexpression might block metastatic progression by influencing the expression of p27 (BRCA1 associated cell cycle inhibitor) and promoting E-Cadherin expression." (PMID 30819139, 2019). "In addition, tumor xenografts derived from si-NR2F1-AS1–transfected HOS cells featured lower FOXA1 protein expression compared with the si-NC group (P < 0.05)." (PMID 31801112, 2019). "In addition, preclinical studies suggest that FOXA1 allows AR to bind to DNA and thereby induce transcription of AR target genes and stimulate tumor proliferation." (PMID 31888566, 2019). "FOXA1, a transcription factor, promotes tumor growth of HCC." (PMID 30782188, 2019). "The 4 IHC markers defining the BASQ subtype of MIBC, CK14-positive, CK5/6-positive, GATA3-negative, FOXA1-negative expression were not readily applicable to non-muscle-invasive papillary UTUC because positivity for CK14 and negativity for GATA3 or for FOXA1 was rarely observed in this tumor." (PMID 30699951, 2019). "Additionally, altered expression of urothelial differentiation factors such as FOXA1 and loss of function mutations in chromatin remodeler proteins such as ARID1A are important in disease progression and contribute to tumor heterogeneity in BC." (PMID 31137849, 2019). "Previous study demonstrated that FOXA1 may be regarded as a potential prognostic marker and may facilitate tumor growth of CRC by upregulating YAP expression." (PMID 30446877, 2019). "Negative FOXA1 expression showed a significant association with higher tumor histological grade (p = 0.016) in 88.2% of tumors." (PMID 31540486, 2019). "In addition, preclinical studies suggest that FOXA1 allows AR to bind to ER DNA binding sites and thereby induce transcription of ER-related genes and thereby stimulate tumor proliferation." (PMID 31888566, 2019). "Patients with AR + /FOXA1 + tumours had a significantly worse OS (p = 0.024)." (PMID 29880907, 2018). "Compared to the other subgroups, FOXA1-/AR- BC phenotype was more frequently associated with high histological grade, large tumor size, no expression of ER and PgR and high proliferation index (P < 0.001)." (PMID 29970021, 2018). "FOXA1 expression was available in 306 patients, including 185 patients (60.5%) with FOXA1 + tumour." (PMID 29880907, 2018). "In luminal androgen receptor (AR) tumours, FOXA1 may direct AR to sites occupied by ER in luminal tumours, thus stimulating proliferation." (PMID 29880907, 2018). "For AR + /FOXA1 + TNBC with a risk of late relapse, an adjuvant anti-androgen therapy could be considered, like in ER + tumours." (PMID 29880907, 2018). "As previously reported, in our cohort FOXA1 positivity was associated with small tumor size (< 15 mm), absence of lymph node metastases, low histological grade, no special type (NST) histotype, low level of Ki67, as well as, with ER+ and PgR+ tumors." (PMID 29970021, 2018). "Patients with AR + /FOXA1 + tumours were significantly older (p = 0.003) than others." (PMID 29880907, 2018). "AR + /FOXA1 + expression defines a luminal-like TNBC subgroup with a worse outcome compared to other TNBC and a higher risk of late recurrences mimicking luminal tumours behaviour and suggesting a putative role for anti-androgen therapies." (PMID 29880907, 2018). "Interestingly, according to analyses of ER-negative tumors using the METABRIC dataset, 18 (4.1%) cases with AR-low/FOXA1-high tumor showed the worst survival and 114 (26.0%) with AR-high/FOXA1-high presented worse DFS with statistical significance." (PMID 29137314, 2017).